MAP3K3 (mitogen-activated protein kinase kinase kinase 3)
Description:
Component of a protein kinase signal transduction cascade. Mediates activation of the NF-kappa-B, AP1 and DDIT3 transcriptional regulators.
Synonyms: MAPKKK3; MEKK3; CCM5
Tractability: Small molecule: a high-quality ligand is known; it belongs to a druggable protein family. PROTAC: ubiquitination databases record sites on it; its protein half-life has been measured; a small molecule that binds it is known.
Target class: Enzyme; STE protein kinase STE11 family; Kinase; Protein Kinase; STE protein kinase MEKK2; STE protein kinase group
Gene: Protein-coding gene on chromosome 17 (63,622,381 to 63,696,305, forward strand). Ensembl gene ENSG00000198909.
Subcellular location (Human Protein Atlas): Nucleoplasm
Pathways (Reactome):
Immune System: Interleukin-1 signaling
Gene Ontology:
Molecular function: protein binding; protein kinase activity; MAP kinase kinase kinase activity; protein serine/threonine kinase activity; ATP binding; protein serine kinase activity
Biological process: intracellular signal transduction; positive regulation of canonical NF-kappaB signal transduction; protein autophosphorylation; MAPK cascade
Cellular component: cytosol
Genetic constraint (gnomAD): Loss-of-function variants: 8 observed, 68.91 expected, observed/expected ratio (o/e) 0.12, 90% interval 0.067 to 0.21. The upper end of that interval is the gene's LOEUF score, 0.21, which puts it in group 1 of 6, group 1 being the genes least tolerant of losing a copy. Missense variants: 533 observed, 787.92 expected, observed/expected ratio (o/e) 0.68, 90% interval 0.63 to 0.73. Synonymous variants: 256 observed, 293.9 expected, observed/expected ratio (o/e) 0.87, 90% interval 0.79 to 0.97.
Homologues: Orthologues: chimpanzee MAP3K3 (99% identical), macaque MAP3K3 (99% identical), pig MAP3K3 (97% identical), rabbit MAP3K3 (97% identical), guinea pig MAP3K3 (97% identical), mouse Map3k3 (97% identical), rat Map3k3 (96% identical), dog MAP3K3 (95% identical), tropical clawed frog map3k3 (84% identical), zebrafish map3k3 (77% identical), Caenorhabditis elegans sek-5 (13% identical), Caenorhabditis elegans sek-4 (12% identical), and 2 more. Paralogues in human: MAP3K2 (65% identical), MAP3K4 (32% identical), NEK1 (18% identical), MAP2K5 (16% identical), MAP2K1 (15% identical), MAP2K7 (15% identical), MAP2K2 (14% identical), MAP2K4 (14% identical).
Diseases named in the same sentence as MAP3K3 in open-access papers:
MAP3K3 is named in the same sentence as 71 diseases in open-access papers, as found by Europe PMC text mining. Sharing a sentence is not in itself a finding about the gene and the disease. The quoted sentences say what the papers report.
cerebral cavernous malformation (13 papers, 2007 to 2026). A disorder characterized by malformations in the structure of the capillaries in the brain. "Somatic p.I441M mutation in MAP3K3 encoding mitogen-activated protein kinase kinase kinase 3 defines a subclass of cerebral cavernous malformation (CCM) and has been recently found to be responsible for VVM." (PMID 37658401, 2023). "It are believed that the mutation of MAP3K3 can define a subclass of cerebral cavernous malformations." (PMID 38260098, 2023). "Loss-of-function mutations in cerebral cavernous malformation (CCM) genes and gain-of-function mutation in the MAP3K3 gene encoding MEKK3 cause CCM." (PMID 36692953, 2023). "Another study has reported that MAP3K3 may be associated with cerebral cavernous malformations." (PMID 38260098, 2023). "We report a loss-of-function, germline, homozygous variant in the AIRE gene associated with APECED syndrome and a gain-of-function variant in mitogen-activated protein kinase kinase kinase 3 (MAP3K3), previously identified in patients with cerebral cavernous malformations (CCMs)." (PMID 41190326, 2025).
breast carcinoma (10 papers, 2015 to 2024). "We found that YAP activity is dependent on MAP3K3 in CDK4/6 inhibitor-resistant breast cancer cells and BRAF inhibitor-resistant melanoma cells." (PMID 38622197, 2024). "Importantly, MAP3K3 knockdown reduced YAP expression in palbociclib-resistant breast cancer cells and downregulated the expression of the YAP target genes CTGF, CYR61, and ANKRD1." (PMID 38622197, 2024). "To investigate whether MAP3K3 inhibition suppresses YAP activity in breast cancer cells resistant to the CDK4/6 inhibitor palbociclib, we established palbociclib-resistant MCF7 (MCF7_PalR) and T47D (T47D_PalR) cell lines by chronic drug administration." (PMID 38622197, 2024). "Furthermore, we demonstrated that pharmacological MAP3K3 inhibition can overcome YAP-induced resistance to CDK4/6 inhibitors in breast cancer cells and to BRAF inhibitors in melanoma cells, underscoring the therapeutic relevance of our findings." (PMID 38622197, 2024). "Many studies have reported that MAP3K3 is highly correlated with the progression and treatment of nasopharyngeal carcinoma, ovarian cancer, lung cancer, and breast cancer." (PMID 38260098, 2023). "Depletion of MAP3K3 led to a substantial reduction in the YAP protein level in melanoma and breast cancer cells." (PMID 38622197, 2024). "In the present study, we found that MAP3K3 regulates YAP in RPE1 and HEK293 cells, as well as in melanoma and breast cancer cells, suggesting that MAP3K3-mediated YAP regulation is a general mechanism." (PMID 38622197, 2024). "Among them were major regulators of breast cancer cell proliferation, including CCND1, LEF1, KLF9, GREB1, or MAP3K3." (PMID 36076907, 2022). "Inhibition of MAP3K3 by shRNA transduction or ponatinib treatment suppressed YAP-dependent resistance to the CDK4/6 inhibitor palbociclib, which is a mainstay targeted therapy for hormone-positive HER2-negative breast cancers." (PMID 38622197, 2024). "Moreover, we show that MAP3K3 inhibition, achieved through RNAi-mediated knockdown or pharmacological means, overcomes CDK4/6 inhibitor resistance in luminal breast cancer cells." (PMID 38622197, 2024). "By stopping MAP3K3, the researchers could lower YAP levels and overcome drug resistance in breast cancer and skin cancer cells." (PMID 38622197, 2024).
lung carcinoma (7 papers, 2014 to 2023). "Higher MAP3K3 expression in normal lung tissues and well-differentiated tumors indicates its potential use as a diagnostic as well as a prognostic marker in lung cancer." (PMID 26088427, 2015). "MAP3K3 gene mutations were detected in 16 out of 1218 (1.3%) lung cancers from the Sanger Sequencing Center and in our data." (PMID 26088427, 2015). "We then analyzed the MAP3K3 protein/mRNA expression in primary lung cancers and its association with clinical-pathological characteristics including patient survival." (PMID 26088427, 2015). "In addition, we investigated MAP3K3 DNA copy number changes, mutation, gene fusion and their relationship in lung cancer." (PMID 26088427, 2015). "The expression and roles of MAP3K3 in lung cancer, however, and its underlying molecular mechanisms remain unknown." (PMID 26088427, 2015). "The AUC (area under the curve) values (normal vs. ADC) from ROC (receiver operating characteristic) curve analysis are 0.93 and 0.94, respectively, for these two RNA-seq datasets indicating that MAP3K3 may potentially be used as diagnostic marker in lung cancer." (PMID 26088427, 2015). "MAP3K3 may potentially not only serve as diagnostic/prognostic markers for patients with lung cancer but also provide an indicator for future investigations into immunomodulatory therapies for lung cancer." (PMID 26088427, 2015). "MAP3K3 acted as a promoter in diverse cancers, including nasopharyngeal carcinoma, lung cancer and pancreatic cancer." (PMID 34789310, 2021). "In this study, we investigated the roles of MAP3K3 in cell proliferation, migration, invasion and effects on cell cycle following MAP3K3 knockdown using siRNA in lung cancer cell lines." (PMID 26088427, 2015). "Silencing MAP3K3 using siRNA in lung cancer cell lines resulted in decreased cell proliferation, migration and invasion." (PMID 26088427, 2015). "In order to test which lung cancer cell line is MAP3K3 dependent, we used siRNA technology to knockdown MAP3K3 expression in 9 lung cancer cell lines." (PMID 26088427, 2015). "The MAP3K3-related pathways discovered by phospho-protein and gene expression arrays in lung cancer cells warrant further study." (PMID 26088427, 2015). "In this study, MAP3K3 promoted tumor growth, migration, invasion and cell cycle regulation in lung cancer cell lines in vitro, but MAP3K3 overexpression in primary lung tumors in vivo was correlated with increased patient survival." (PMID 26088427, 2015). "The biological function of MAP3K3 in lung cancer is poorly understood." (PMID 26088427, 2015). "MAP3K3 mRNA expression and its relationship to clinical-pathological variables, including patient survival in lung cancer tissues, has not been reported." (PMID 26088427, 2015). "As compared to non-target siRNA, treatment with MAP3K3 siRNA resulted in a significant decrease in cell proliferation in these 5 lung cancer cell lines." (PMID 26088427, 2015). "Furthermore, our study revealed that MAP3K3 regulates the cell cycle through effects on CDC25A, CCND1/2 and CCNE1 regulation in lung cancer." (PMID 26088427, 2015). "MAP3K3 and MAP3K14 are in the MAPK/ERK pathway which is a target of many novel therapeutic agents, and SRC is a well known oncogene and a candidate target in lung cancer." (PMID 25170874, 2014).
ovarian carcinoma (7 papers, 2014 to 2025). A malignant neoplasm originating from the surface ovarian epithelium. "It has been demonstrated that overexpression of MAP3K3 plays a role in regulating NF-κB signaling through TNF in ovarian carcinoma." (PMID 41190326, 2025). "Increased expression of MAP3K3 in ovarian cancer, esophageal and breast cancer has been reported to be associated with tumorigenesis." (PMID 30652073, 2019).
pancreatic cancer (7 papers, 2021 to 2024). "A recent study reported the requirement of MAP3K3 for YAP target gene transcription in pancreatic cancer cells." (PMID 38622197, 2024). "They reported significantly decreased expression of YAP target genes in MAP3K3-null pancreatic cancer cells." (PMID 38622197, 2024). "YAP/TAZ, in some instances, acts downstream of MEKK3 (or MAP3K3) to maintain stemness in pancreatic cancer cells." (PMID 38607003, 2024). "These in silico results were validated using 43 pairs of resected pancreatic cancer samples, which also showed that the expression levels of MAGEH1, MAP3K3 and PODN were downregulated in tumor tissues." (PMID 33912458, 2021).
serous ovarian cancer (7 papers, 2021 to 2024). "MAP3K3 (mitogen-activated protein kinase kinase kinase 3) was a target of miR-129-3p in serous ovarian cancer cells." (PMID 38152652, 2023). "For instance, miR-212–3p in HGSOC inhibited cell invasion, proliferation, and migration by targeting MAP3K3 in high-grade serous ovarian cancer." (PMID 36386819, 2022). "Moreover, studies have indicated that overexpression of miR-212-3p can also suppress MAP3K3 protein expression, further inhibiting cell invasion, proliferation, and migration in certain cancers, such as high-grade serous ovarian cancer (HGSOC)." (PMID 39777350, 2024). "Overexpression of lncRNA CTBP1-DT could competitively bind to miR-188-5p to protect MAP3K3 from degradation, which could promote malignant biological behaviors of HGSOC (high-grade serous ovarian cancer) cells." (PMID 36739404, 2023).
nasopharyngeal carcinoma (5 papers, 2019 to 2023). A carcinoma arising from the nasopharyngeal epithelium. "Here, we for the first time reported a function of miR‐194 in nasopharyngeal carcinoma and established an association between miR‐194 and MAP3K3, which is in line with the inhibitory role of miR‐194 in cancer regression." (PMID 30652073, 2019). "Although we explored the role of miR‐194 on MAP3K3, it would be interesting to investigate the expression changes of MAP3K3 in tumor tissue specimens to decipher its independent tumorigenesis in nasopharyngeal carcinoma." (PMID 30652073, 2019). "All of these results indicated that MAP3K3 is a direct target of miR‐194, and miR‐194 inhibits the nasopharyngeal carcinoma progression through modulating MAP3K3." (PMID 30652073, 2019). "MAP3K3 expression was much higher in nasopharyngeal carcinoma cell lines (CNE‐1, CNE‐2, HONE‐1, HNE‐1, C666‐1 and SUNE‐1) when compared to that in nasopharyngeal epithelial cell line NP69." (PMID 30652073, 2019). "We found that miR‐194 binds the 3′ untranslated region of MAP3K3, and knockdown of miR‐194 inhibited nasopharyngeal carcinoma cell proliferation, migration and invasion." (PMID 30652073, 2019). "This study suggests that expression of miR‐194 is down‐regulated in nasopharyngeal carcinoma, and that miR‐194 can directly target MAP3K3 to regulate tumor progression." (PMID 30652073, 2019). "In addition, we found MAP3K3 knockdown inhibited nasopharyngeal carcinoma cell proliferation, migration and invasion." (PMID 30652073, 2019). "However, the clinical significance of MAP3K3 expression in nasopharyngeal carcinoma remains elusive." (PMID 30652073, 2019). "Given the pivotal involvement of MAP3K3 in nasopharyngeal carcinoma development, targeting miR‐194 may be a novel strategy for the treatment of nasopharyngeal carcinoma." (PMID 30652073, 2019). "In this study, we confirmed the knockdown of MAP3K3 in human nasopharyngeal carcinoma cell lines by shRNA significantly inhibited the nasopharyngeal carcinoma cell proliferation, migration and invasion, indicating the prognostic role of MAP3K3 in the pathogenesis of nasopharyngeal carcinoma." (PMID 30652073, 2019). "Although aberrant expression of miR‐194 and MAP3K3 in different cancer cells has been shown to suppress tumor cell invasion and metastasis, little is known about their role in regulating the progression of nasopharyngeal carcinoma." (PMID 30652073, 2019). "As MAP3K3 is critically involved in nasopharyngeal carcinoma development, exploiting the suppressive role of miR‐194 on nasopharyngeal carcinoma might be an effective rationale for diagnosis and treatment of nasopharyngeal carcinoma." (PMID 30652073, 2019).
non-small cell lung carcinoma (5 papers, 2019 to 2024). A group of at least three distinct histological types of lung cancer, including non-small cell squamous cell carcinoma, adenocarcinoma, and large cell carcinoma. "Another study showed that miR-380 passed NF κ Pathway B targets MAP3K3 to inhibit the proliferation of non-small cell lung cancer cells." (PMID 38582841, 2024). "In non-small-cell lung cancer, XIST has been reported to regulate the cell proliferation and apoptosis by modulating the MAP3K3 pathway, and the MAPK pathway was associated with the PD pathogenesis." (PMID 30867898, 2019). "The epidermal growth factor receptor (EGFR) can recruit mitogen-activated protein kinase kinase kinase 3 (MEKK3) in a tumor necrosis factor receptor (TNF-R)-associated factor 4 (TRAF4)-dependent manner, which activates ERK5 and supports the proliferation of non-small-cell lung cancer cells." (PMID 38785963, 2024).
Parkinson disease (4 papers, 2018 to 2023). A progressive degenerative disorder of the central nervous system characterized by loss of dopamine producing neurons in the substantia nigra and the presence of Lewy bodies in the substantia nigra and locus coeruleus. "The expression of MAP3K3 was significantly associated with Fc gamma R-mediated phagocytosis, osteoclast differentiation, oxidative phosphorylation, Parkinson’s disease, and ribosomes." (PMID 38260098, 2023).
prostate carcinoma (4 papers, 2015 to 2020). A carcinoma that arises from epithelial cells of the prostate gland. "First, p62 binds to mitogen-activated protein kinase kinase kinase 3 (MEKK3) through an N-terminal oligomerization domain (PB1), which leads to mTORC1 activation and c-Myc expression, thus promoting cancer cell proliferation in prostate cancer stromal fibroblasts and HCC." (PMID 31708690, 2019).
gastric cancer (3 papers, 2019 to 2025). A primary or metastatic malignant neoplasm involving the stomach. "In the existing research, OGFRP1 was investigated to enhance the growth of gastric cancer cells and inhibit cell death and sensitivity to radiation by controlling the miR-149-5p/MAP3K3 pathway, which has been demonstrated to play a similar role in choriocarcinoma through the miR-4731-5p/HIF3A axis." (PMID 39352634, 2025).
hemorrhage (3 papers, 2015 to 2025). Loss of blood from the vascular compartment to the exterior or into nonvascular body space as a result of rupture or severance of the blood vessels. "We examined the association between PIK3CA and MAP3K3 mutations and hemorrhage during the follow-up after CM diagnosis." (PMID 40478424, 2025). "Multivariate logistic analyses revealed that MAP3K3 mutation was associated with a lower risk of hemorrhage events." (PMID 36090889, 2022). "Simplex CCMs with MAP3K3 mutation occasionally present with overt hemorrhage, which is associated with the biological function of MAP3K3 mutation." (PMID 36090889, 2022). "Compared with CCM gene mutations, simplex CCMs with MAP3K3 mutation occasionally present with overt hemorrhage, which is associated with the biological function of MAP3K3 mutation in the endothelium." (PMID 36090889, 2022). "We hypothesized that MAP3K3 mutations were associated with a lower risk of hemorrhage events that might result from the biofunction features of the MAP3K3 mutation concerning the expression of TM and TJ proteins." (PMID 36090889, 2022). "A recent study showed that patients with PIK3CA mutations had a higher rate of hemorrhage as the initial symptom of CCM diagnosis than those with only the MAP3K3 I441M mutation and those with both the PIK3CA mutation and the MAP3K3 I441M." (PMID 40478424, 2025).
Sepsis (3 papers, 2023 to 2026). Sepsis is defined as life-threatening organ dysfunction caused by a dysregulated host response to infection. "We expanded our research to a broader range of inflammatory models, such as LPS-induced sepsis, and found that MAP3K3 deficiency also led to impaired diapedesis." (PMID 41356186, 2026). "Furthermore, we observed that in both baboon sepsis models, 3 other miR-93-5p targets, ZAP70, MAP3K3, and MAP4K2, were downregulated after induction of sepsis." (PMID 37261908, 2023).
atherosclerosis (2 papers, 2021 to 2023). A disease characterized by the build-up of fatty material and calcium deposition in the arterial wall resulting in partial or complete occlusion of the arterial lumen. "Among them, ANXA2, ApoA1, PGK1, CEBPB and MAP3K3 were related to atherosclerosis and cerebral inflammation." (PMID 34295249, 2021).
cervical cancer (2 papers, 2016 to 2024). A primary or metastatic malignant neoplasm involving the cervix. "Elevated MAP3K3 expression is also associated with the progression and prognosis of several cancers, such as esophageal squamous cell carcinoma, cervical cancer, and ovarian cancer." (PMID 38622197, 2024). "Moreover, MAP3K3 upregulation is associated with poor survival in esophageal squamous cell carcinoma, cervical cancer, and ovarian cancer." (PMID 38622197, 2024).